CXCL12 (C-X-C motif chemokine ligand 12)
Diseases named in the same sentence as CXCL12 in open-access papers (continued):
Sharing a sentence is not in itself a finding about the gene and the disease.
scleroderma (4 papers, 2022 to 2025). Scleroderma is a rare autoimmune connective tissue disorder characterized by abnormal hardening of the skin and, sometimes, other organs. "Our fibroblasts in NEOLP and EOLP shared transcriptional similarity with fibroblasts from skins of scleroderma patients (including CCL19+APOE+CXCL12+ fibroblasts and SFRP2+PRSS23+ fibroblasts), which indicated an overlap between inflammatory features of fibroblasts across OLP and other diseases." (PMID 40574847, 2025). "In contrast, activated sublining FLS were transcriptionally similar to ACTA2+ myofibroblasts and WNT5B+ fibroblasts in the colon as well as two populations of dermal fibroblasts expanded in scleroderma as compared to healthy skin (CCL19+APOE+CXCL12+ and SFRP2hiPRSS23+THY1+)." (PMID 37277655, 2023). "In addition, we evaluated the relevant infoammatory cytokines of IL1, IL6, IL12,TNFα, and CXCL12 in the normal, scleroderma and treatment groups, respectively." (PMID 35315234, 2022). "Similar CXCL12-mediated fibroimmune mechanisms may be operative in other chronic inflammatory or fibrotic skin diseases such as lichen planopilaris, chronic graft-versus-host disease, or even scleroderma." (PMID 40724819, 2025).
Thrombocytopenia (4 papers, 2014 to 2024). A reduction in the number of circulating thrombocytes. "As megakaryocyte migration to the sinusoidal niche, mediated by CXCL12 signalling, is a key step in thrombopoiesis, these findings may explain observations of thrombocytopenia as an adverse effect in clinical trials investigating the potential use of Pim kinase inhibitors as cancer treatments." (PMID 39062849, 2024).
uveal melanoma (4 papers, 2007 to 2024). A melanoma derived from melanocytes of the uveal tract. "CXCR4 is expressed in uveal melanoma cells, and it is known that ligand CXCL12 is expressed in the liver." (PMID 38732371, 2024). "We sought to characterize the presence of the CXCR4/CXCL12 axis in five uveal melanoma (UM) cell lines in vitro." (PMID 18001467, 2007). "This suggests that human uveal melanoma cell lines will be more likely to have a greater metastatic potential than other cell lines that actively produce CXCL12 thus creating an autocrine signaling loop." (PMID 18001467, 2007). "The migratory ability of the 5 human uveal melanoma cell lines was positively influenced by the four chemotactic factors tested, namely CXCL12, CXCL8, CXCL1, and HGF." (PMID 17261188, 2007). "Our laboratory has previously shown that uveal melanoma cellular migration can be induced in vitro when exposing uveal melanoma cell lines to exogenous sources of CXCL12." (PMID 18001467, 2007). "The key to senescent cell-induced tumor metastasis is SASP secreted by senescent cells, and we confirmed that the most critical component of the SASP leading to metastasis in uveal melanoma is CXCL12, a chemokine that has been widely shown to promote tumor metastasis." (PMID 38951874, 2024). "In uveal melanoma, the pattern of metastatic spread is predominantly to the liver, therefore suggesting that CXCL12 expression in the liver may be involved in the homing of uveal melanoma cells to this site." (PMID 17261188, 2007). "The aim of this study was to characterize the presence and roles of CXCL12, CXCL8, CXCL1, and HGF in five human uveal melanoma cell lines, using different methods, in order to ascertain their significance in this disease." (PMID 17261188, 2007). "In conclusion, characterizing the expression of CXCL12, CXCL8, CXCL1, and HGF in uveal melanoma cell lines leads us to a better understanding of how these cytokines are integral in the metastatic process." (PMID 17261188, 2007). "The present study was designed in order to analyze the expression of CXCL12, CXCL8, CXCL1, and HGF in five human uveal melanoma cell lines (92.1, SP6.5, MKT-BR, OCM-1, UW-1) and to investigate the effects of these factors on the migratory ability of the 5 cell lines." (PMID 17261188, 2007). "Demonstration of a functional role for CXCL12, CXCL8, CXCL1, and HGF in uveal melanoma may yield novel therapeutic targets." (PMID 17261188, 2007). "In our study, none of the 5 human uveal melanoma cell lines expressed any detectable levels of CXCL12." (PMID 17261188, 2007). "We have also shown that uveal melanoma cell lines (92.1, SP6.5, MKT-BR, OCM-1, UW-1) do not express any detectable levels of CXCL12 when analyzed with quantitative real-time PCR." (PMID 18001467, 2007).
abdominal aortic aneurysm (3 papers, 2022 to 2025). Enlargement and ballooning of the vessel that supplies arterial blood to the abdomen, pelvis and legs. "Notably, the C‐X‐C Motif Chemokine Ligand 12/C‐X‐C Chemokine Receptor Type 4 (CXCL12/CXCR4) signalling pathway's activation is markedly increased in a mouse model of abdominal aortic aneurysms (AAA)." (PMID 39779470, 2025). "Previous studies have shown that T and B cells infiltrated in abdominal aortic aneurysms are CXCR4-positive and are recruited by CXCL12-positive stromal cells." (PMID 35837612, 2022).
adenomyosis (3 papers, 2018 to 2023). The growth of endometrial tissue inside the muscular wall of the uterine corpus. "The levels of CXCL12 and its receptor, chemokine (C-X-C motif) receptor 4 (CXCR4), were found to be significantly increased in both eutopic and ectopic endometrium from patients with adenomyosis." (PMID 35022045, 2022).
AIDS dementia (3 papers, 2007 to 2018). "Interestingly, the MMP-2 cleavage and inactivation of CXCL12 in the brain generates a potent and selective neurotoxin implicated in HIV dementia." (PMID 17375198, 2007). "On the other hand, elevated levels of CXCL12 mRNA have been reported for brain specimen from HIV encephalitis (HIVE) patients as compared to uninfected controls, and we and others have shown that protein expression of CXCL12 also appears to be elevated in the brains of HIV patients." (PMID 27664068, 2016).
allergic asthma (3 papers, 2013 to 2024). A asthma with a basis in a pathological type I hypersensitivity reaction. "First, this study investigated the impact of LIT-927 treatment at a single concentration and duration of treatment; extensive dose- and time-response experiments are certainly warranted to more fully investigate the potential of CXCL12 neutralization as a therapy for allergic asthma." (PMID 35831901, 2022).
allergic disease (3 papers, 2009 to 2018). An immune response that occurs following re-exposure to an innocuous antigen, and that requires the presence of existing antibodies against that antigen. "This is based largely on evidence that stem cells or CD34+ progenitor cells are recruited to the site of inflammation in allergic diseases, likely through many of the same adhesion and chemokine receptors used for stem cell homing to the bone marrow (PSGL-1, CXCL12, α4β1 integrin, CD44, etc)." (PMID 20066174, 2009).
alopecia areata (3 papers, 2024). Loss of scalp and body hair involving microscopically inflammatory patchy areas. "In addition, the CXCL12 level was increased in the dermal papilla region of alopecia areata (AA) patients and is regarded as a stress-sentinel that activates immune cells." (PMID 39795953, 2024). "Therefore, we further investigated whether a CXCL12 neutralizing antibody (αCXCL12) is effective for androgenic alopecia (AGA) and alopecia areata (AA) and studied the underlying molecular mechanism for treating these diseases." (PMID 38338982, 2024). "It has been demonstrated that CXCL12 inhibits hair growth via CXCR4, and its neutralizing antibody (Ab) increases hair growth in alopecia areata (AA)." (PMID 39483478, 2024).
androgenic alopecia (3 papers, 2024). "We further demonstrated that the CXCL12-neutralizing antibody promotes hair growth in androgenic alopecia (AGA) and AA." (PMID 39795953, 2024). "We previously demonstrated that C-X-C Motif Chemokine Ligand 12 (CXCL12) is primarily secreted by dermal fibroblasts in response to androgens and induces hair miniaturization in the mouse androgenic alopecia (AGA) model." (PMID 39795953, 2024). "In androgenic alopecia (AGA) mice, CXCL12 is up-regulated in DFs, and CXCL12-neutralizing Ab promoted hair growth in a dose-dependent manner." (PMID 39483478, 2024).
arteriosclerosis (3 papers, 2019 to 2025). A vascular disorder characterized by thickening and hardening of the walls of the arteries. "This establishes a positive autoregulatory feedback loop that promotes CXCL12 secretion and CXCL12-dependent vascular protection, ultimately inhibiting the formation of calcified plaques and progression of arteriosclerosis." (PMID 40747304, 2025). "In addition to pro-inflammatory cytokines such as TNF-α, IL-1β, IL-6, and MCP-1, chemokines such as macrophage migration inhibitory factor and CXCL12 play an important role in the initiation and the progression of arteriosclerosis." (PMID 36670934, 2022). "CXCL12 can also play a crucial role in the accumulation of smooth muscle progenitor cells (SPCs), participate in the inflammatory response and induce endothelial cells differentiation into foam cells, eventually lead to arteriosclerosis." (PMID 30844764, 2019).
bladder tumors (3 papers, 2021 to 2022). "In our study, CXCL12 was found to be widely expressed in the fibroblasts of paraneoplastic tissues of bladder tumors by single cell sequencing analysis and immunohistochemistry." (PMID 36211359, 2022). "To further discuss the potential mechanisms of CXCL12 expression reduction in BLCA pathogenesis, we analyzed the DEGs between normal and bladder tumor tissues." (PMID 34801033, 2021). "Comparison of chemoattractants expression during MB49 bladder tumors grow highlighted CCL8 and CCL12 (CCR2-ligands), CCL9 and CCL6 (CCR-1-ligands), CXCL2 and CXCL5 (CXCR2-ligands), CXCL12 (CXCR4-ligand) and antagonist of C5/C5a as potential targets to decrease myeloid suppressive cells." (PMID 36613562, 2022).
bladder urothelial carcinoma (3 papers, 2020 to 2022). "Subcluster F0 was the primary fibroblast type in PT and M and strongly expressed PDGFRA and CXCL12, similar to that in the iCAFs described in bladder urothelial carcinoma." (PMID 35184420, 2022). "Immunohistochemistry and online analyses validated the functions of 4 key immune-related genes (LIG1, TBX1, CTSG and CXCL12) in bladder urothelial carcinoma." (PMID 32579540, 2020).
clear cell renal cell carcinoma (3 papers, 2022 to 2024). "In contrast, MSC-2 clusters derived from the bone marrow of patients with clear cell renal cell carcinoma metastases maintained the classic MSC markers NT5E and THY1 (CD90), but the expression of VCAM1, LEPR, and CXCL12 was reduced." (PMID 39156727, 2024).
cognitive decline (3 papers, 2019 to 2025). "One chemokine, for which decline has been associated with cognitive decline in AD, CXCL12, was significantly down-regulated (p = 0.0006) in concussed brains." (PMID 31727161, 2019). "C‐X‐C chemokine receptor type 4 (CXCR4) synergizes with the chemokine CXCL12 to mediate inflammatory responses and cognitive decline in patients with AD." (PMID 37334737, 2023).
colorectal adenocarcinoma (3 papers, 2020 to 2023). The most common type of colorectal carcinoma. "Colorectal adenocarcinoma cell proliferation and migration are facilitated by SNHG17 through inhibition of miR-23a-3p, which modifies CXCL12-mediated angiogenesis." (PMID 38004422, 2023).
encephalitis (3 papers, 2014 to 2016). An acute inflammatory process affecting the brain parenchyma. "During WNV encephalitis, levels of abluminal CXCL12 along the microvasculature drop when compared with uninfected counterparts suggesting a mechanism for promoting leukocyte entry for viral clearance." (PMID 26556427, 2014). "CXCL12 expression at the microvasculature localizes immune cells, promoting their interaction within perivascular spaces, regulating the entry of fully activated WNV-specific T lymphocytes during WNV encephalitis." (PMID 26556427, 2014). "However the reason for the observed discrepancies in CSF CXCL12 levels between ADEM and the other two groups of encephalitis (EVE and anti-NMDAR E) is not clear." (PMID 27575749, 2016).
endotoxemia (3 papers, 2015 to 2024). "Also, we aimed to indirectly show that CTCE-0214D signals through CXCR4 and to further unravel whether an interruption of the CXCR4/CXCL12 axis results in a deleterious outcome in endotoxemia." (PMID 27716214, 2016). "Nevertheless, the existing data concerning the role of the CXCR4/CXCL12 axis in inflammatory diseases remains contradictious and up to now, no further investigations were carried out to determine what exact effects a CXCL12 analog exerts in endotoxemia systemically and in the organs." (PMID 26375818, 2015). "This suggests that interruption of the CXCR4/CXCL12 axis is deleterious in acute inflammation and confirms previous findings showing beneficial effects of CXCR4 agonists in endotoxemia, thereby more clearly elucidating the role of CXCR4 in inflammation." (PMID 27716214, 2016). "In addition, by detecting effects with the CXCR4 antagonist, AMD3100, that are in direct contrast to those observed with the CXCL12 analog, CTCE-0214D, in endotoxemia, we can hypothesize that treatment with CTCE-0214D exerts its protective effects mainly via CXCR4." (PMID 27716214, 2016).
gastritis (3 papers, 2021 to 2025). Inflammation of the stomach. "In addition, the high expression of BHLHE40 in gastric epithelial cells increased the production of CXCL12 by interacting with p-STAT3 in Helicobacter pylori-associated gastritis, which further aggravated the development of gastritis." (PMID 34917665, 2021).
gout (3 papers, 2019 to 2025). A condition characterized by painful swelling of the joints, which is caused by deposition of urate crystals. "Kim found that gout patients showed a higher expression of CXCL12 and proinflammatory cytokines, including IL-1β and IL-18, than members of the control group." (PMID 40444241, 2025). "First, the size of the study population, including the gout patients and controls, was relatively small to clarify the differences between CXCL12 and CXCR4." (PMID 36979628, 2023). "We found that gout patients showed a higher expression of CXCL12 and proinflammatory cytokines, including IL-1β and IL-18, than members of the control group." (PMID 36979628, 2023). "Nevertheless, the CXCL12/CXCR4 axis plays a critical role in immune-mediated or inflammatory diseases (including gouty arthritis) as a therapeutic target by modulating the inflammatory and immune response and regulating the recruitment of leukocytes." (PMID 36979628, 2023). "The aim of this study was to evaluate the expression of chemokine receptor CXCR4 and its ligand CXCL12 in patients with gout and uric acid-induced inflammation." (PMID 36979628, 2023). "In a comparison of CXCR4 and its ligand CXCL12, the gout patients showed a larger increase in the expression of the serum CXCL12 level compared with the controls (392.27 ± 247.54 vs. 243.90 ± 184.03, p = 0.010)." (PMID 36979628, 2023). "Considering the interactions between gout and the downstream pathways in the CXCL12/CXCR4 axis, many studies have suggested that the uric acid-induced inflammatory response with activation by NF-κB might be related to the GPCR downstream signaling pathway." (PMID 36979628, 2023). "Thus, the aim of this study was to compare the CXCR4 and CXCL12 levels between gout patients and controls and to determine the role of these molecules in uric acid-induced inflammation." (PMID 36979628, 2023). "We evaluated the relationship among IL-1β, IL-18, CXCL12, CXCR4, and the laboratory variables in the patients with gout." (PMID 36979628, 2023). "In the present study, we confirmed that the IL-1β and IL-18 expression was increased by a stimulation with MSU crystals as well as in the blood of gout patients, together with CXCR4 and CXCL12." (PMID 36979628, 2023). "In this study, we revealed that CXCL12 and CXCR4 were involved in the pathogenesis of uric acid-induced inflammation and gouty arthritis." (PMID 36979628, 2023). "Therefore, chemokine CXCL12 and its receptor CXCR4 might be considered to be potent therapeutic targets in uric acid-induced NLRP3 inflammasome activation in gout patients." (PMID 36979628, 2023).
Granuloma (3 papers, 2013 to 2024). A compact, organized collection of mature mononuclear phagocytes, which may be but is not necessarily accompanied by accessory features such as necrosis. "By employing spatial transcriptomics, Sati and authors found that CXCL12 expression was localized in the granulomas of sarcoidosis-affected tissues." (PMID 39225095, 2024). "Together, our data illustrate a pathway through which pathogenic mycobacteria induce host miR-206 expression to suppress Cxcl12/Cxcr4 signalling and prevent protective neutrophil recruitment to granulomas." (PMID 33826679, 2021). "Taken together, their results show that CXCL12-expressing fibroblasts in the granulomas may recruit CXCR4-expressing immune cells, resulting in the formation of granulomas." (PMID 39225095, 2024).
hair loss (3 papers, 2024 to 2025). "Collectively, these results indicate that CXCL12 is involved in the progression of AGA and AA and antibody therapy for CXCL12 is promising for hair loss treatment." (PMID 38338982, 2024).
Hodgkins lymphoma (3 papers, 2012 to 2016). A heterogeneous group of malignant lymphoid neoplasms of B-cell origin characterized histologically by the presence of Hodgkin and Reed-Sternberg (HRS) cells in the vast majority of cases. "Furthermore, in studying the CXCL12-induced phosphoproteome adjustments in Hodgkin's lymphoma-derived L540 cells, which do not express HER1 but other HER receptors, we found that HER2 phosphorylation is strongly downregulated 20 minutes after stimulation with CXCL12." (PMID 22529914, 2012).
hypertrophic cardiomyopathy (3 papers, 2016 to 2021). A condition in which the myocardium is hypertrophied without an obvious cause. "As a link to human pathology, two studies in human subjects suffering from hypertrophic cardiomyopathy (HCM) showed elevated plasma levels of CXCL12 related to increased diffuse fibrosis, also suggesting an important role of CXCL12 in human pathology." (PMID 34072818, 2021).
lymphocytic leukemia (3 papers, 2014 to 2023). "Finally, there is one CXCL12 antagonist, olaptesed pegol (NOX-A12), a pegylated structured L-oligoribonucleotide that binds and neutralizes CXCL12, which is in a phase 2a study of relapsed and refractory lymphocytic leukemia (NCT01486797)." (PMID 32260318, 2020).
malignant mesothelioma (3 papers, 2011 to 2021). A malignant neoplasm of the pleura or peritoneum, arising from mesothelial cells. "Importantly, while CXCL12 promotes tumor cell proliferation, BoxA reduces it, and might be exploited for the treatment of malignant mesothelioma and a variety of other tumors." (PMID 33956406, 2021).
monocytic leukemia (3 papers, 2015 to 2022). "In this study, we observed the inhibitory effect of ginsenoside Rk3 on the EMI of monocytic leukemia cells and initially explored its related mechanism of targeting the miR-3677-5p/CXCL12 axis." (PMID 36569343, 2022). "The experimental results above indicate that the miR-3677-5p/CXCL12 axis may be closely related to the occurrence of EMI in monocytic leukemia." (PMID 36569343, 2022). "Therefore, we studied the effects of miR-3677-5p and CXCL12 expression on the proliferation, migration, and invasion of SHI-1 cells and explored the active mechanism of Rk3 for anti-EMI in monocytic leukemia cells." (PMID 36569343, 2022). "Therefore, miR-3677-5p and CXCL12 may be used as indicators of EMI and poor prognosis in monocytic leukemia." (PMID 36569343, 2022).